INS (insulin)
Diseases named in the same sentence as INS in open-access papers (continued):
Sharing a sentence is not in itself a finding about the gene and the disease.
Insulin resistance (continued). "Recently, insulin resistance (IR), characterized by reduced sensitivity or reactivity to insulin’s metabolic effects, including insulin-mediated glucose handling, has been widely recognized as an independent risk factor for stroke." (PMID 40969601, 2025). "Hyperinsulinemia and peripheral insulin resistance, particularly in the early stage of type 2 DM, have been reported to induce a deficit in insulin transport across the blood–brain barrier." (PMID 40013915, 2025). "In cases of insulin resistance, however, tissues respond poorly to insulin, leading to impaired glucose regulation." (PMID 41375973, 2025). "Dysregulation of the expression of this miR can suppress the insulin signaling cascade, which can lead to insulin resistance and type 2 diabetes." (PMID 40217882, 2025). "This enhances insulin signaling pathway activity and effectively reduces peripheral insulin resistance." (PMID 41357185, 2025). "Key markers, including luteinizing hormone (LH), anti-Müllerian hormone (AMH), insulin, and Homeostatic Model Assessment for Insulin Resistance (HOMA-IR), reflect disruptions in the hypothalamic-pituitary-ovarian axis and metabolic homeostasis." (PMID 41220482, 2025). "The findings of this study demonstrate that short-term VLCD treatment facilitates effective weight management, enhances insulin sensitivity, and reduces insulin resistance which are pivotal in the therapeutic management of MetS." (PMID 41458553, 2025). "Hyperinsulinemia and insulin resistance further promote thyroid carcinogenesis by activating the insulin/IGF-1–MAPK–PI3K signaling pathways, stimulating cell proliferation and inhibiting apoptosis." (PMID 41515940, 2025). "The research has indicated that pancreatic injury or pancreatic tissue damage often leads to insufficient insulin secretion or insulin resistance, which in turn affects blood glucose processing and increases blood glucose levels." (PMID 40725244, 2025). "It is characterised by chronic hyperglycaemia resulting from insulin resistance and/or impaired insulin secretion." (PMID 40724114, 2025). "In adipose tissue, for example, persistent SASP factors such as IL-6 and MCP-1 disrupt insulin signaling and promote macrophage infiltration, linking senescent cell buildup to metabolic dysfunction and insulin resistance." (PMID 41465170, 2025). "In this study, both glucose tolerance and insulin sensitivity exhibited significant declines at week 8, progressively diminishing by week 12, indicative of the stabilization of the insulin resistance model by the 12th week." (PMID 39761309, 2025). "Insulin resistance – another component of metabolic syndrome – also plays a role, with women who develop preeclampsia more likely to be insulin resistant compared to normotensive women." (PMID 39976766, 2025). "A 12-week trial in 48 patients with Type 2 DM showed that vitamin D supplementation after 3 months reduced biochemical markers, IL-6, fasting insulin, and homeostatic model assessment for insulin resistance levels." (PMID 40041571, 2025). "In particular, insulin resistance in AT plays a central role: when AT approaches its limit for lipid storage, an inflammatory response is triggered and its ability to respond to insulin diminishes." (PMID 40905018, 2025). "Although insulin promotes fatty acid synthesis, de novo lipogenesis in the liver is further enhanced in insulin resistance, contributing to MASLD." (PMID 40286055, 2025). "In this study, we explore the relationship between SUA and fasting plasma glucose (FPG), insulin levels, and insulin resistance in an older Finnish adult cohort." (PMID 40283451, 2025). "Although HOMA-IR (homeostasis model assessment of insulin resistance) is commonly employed to evaluate insulin resistance, it requires fasting glucose and insulin level measurements." (PMID 40724174, 2025).
Insulin resistance (continued). "Many studies have indicated that early application of insulin is beneficial in reducing insulin resistance, reversing glucose toxicity, and preserving islet B cell function." (PMID 40641746, 2025). "This interaction highlights the dual role of inflammation in the pathogenesis of GDM, both through the induction of insulin resistance and through the dysfunction of compensatory mechanisms of insulin secretion." (PMID 40722699, 2025). "Oxidative stress also contributes to insulin resistance by weakening the ability of insulin to assist cellular glucose intake." (PMID 41012578, 2025). "The QUICKI index, widely used to estimate insulin sensitivity, showed a significant decrease in rodents subjected to MS, suggesting a pattern consistent with insulin resistance." (PMID 41155221, 2025). "Hyperexpression of miR-143 causes insulin resistance due to inhibition of the protein bound to oxysterol and block of activation of the PI3K/AKT pathway by insulin." (PMID 40217882, 2025). "Conversely, SD-OP animals exhibited hyperinsulinemia and insulin resistance, with elevated serum insulin and HOMA-IR levels, suggesting that a high-carbohydrate diet exacerbates insulin resistance and promotes obesity." (PMID 40622971, 2025). "There is an initial surge in insulin sensitivity within 2 h of giving LPS, followed by the emergence of insulin resistance after several hours." (PMID 39838305, 2025). "CRH, by definition, resist insulin’s signaling—thus leading to the phenotype of insulin resistance: high blood sugar and high insulin occurring simultaneously, and continuously." (PMID 40421040, 2025). "The intervention was associated with modest improvements in glycemic regulation, as evidenced by reductions in fasting blood glucose, serum insulin, and the homeostatic model assessment for insulin resistance (HOMA-IR)." (PMID 40649724, 2025). "Physical exercise normalizes these levels by reducing serum insulin, insulin resistance, and fasting glycemia; lowering serum leptin and leptin resistance; and by increasing serum adiponectin." (PMID 40002337, 2025). "Baseline and 12-week assessments consisted of fasting blood glucose (FBG), serum insulin, HbA1c, lipid profile, BMI, and homeostatic model assessment of insulin resistance (HOMA-IR)." (PMID 40861594, 2025). "Insulin resistance and glycemic dysregulation are strongly associated with PCOS, leading to elevated circulating insulin levels." (PMID 40776915, 2025). "Both of these factors, as well as the interaction between INS and MAFLD, are associated with insulin resistance, which has been widely confirmed as a predictor of MAFLD." (PMID 39844086, 2025). "Outcomes on BMI reduction, stabilization, and maintenance ranked lowest, as well as fitness testing measures, adipose tissue hormones, fasting insulin or glycemia, and insulin resistance." (PMID 40747786, 2025). "Other evidence has confirmed the involvement of miR-24-3p, miR-223-3p, and miR-375-5p in glucose regulation, insulin secretion and insulin resistance." (PMID 41295241, 2025). "ITT is effective in predicting the efficacy of insulin sensitizers, and the insulin resistance indicated by ITT results can aid in improving blood glucose control in patients with T2DM." (PMID 39815341, 2025). "The AGE-RAGE interaction also contributes to the development of insulin resistance, a key symbol of type 2 diabetes, by disrupting insulin signaling pathways and impairing glucose uptake in peripheral tissues such as muscle and adipose tissue." (PMID 41150789, 2025). "Approximately 50% of women with GDM will have systemic insulin resistance, 35% will display insufficient insulin secretion, and 15% will exhibit variations of altered insulin metabolism." (PMID 40636710, 2025). "Using the HOMA‐IR calculation, we calculated insulin resistance values based on the corresponding AUC values reflecting the cumulative insulin and glucose responses at 15, 40, and 60 min after the start of the exercise." (PMID 40574473, 2025).
Insulin resistance (continued). "The euglycemic insulin clamp and intravenous glucose tolerance test are recognized as the gold standards for assessing insulin resistance (IR)." (PMID 40164755, 2025). "The significant characteristics of T2D are reduced insulin generation and disturbed insulin secretion, which contribute to insulin resistance." (PMID 40566527, 2025). "Several studies discovered that okra, particularly its polysaccharides, were antagonists of PPARs, which ameliorated insulin resistance and insulin sensitivity." (PMID 39856844, 2025). "In this study, we aimed to investigate the relationships among insulin secretion, insulin resistance, and cortisol or aldosterone levels in patients with untreated type 2 diabetes." (PMID 40296149, 2025). "Indirect measurements of insulin resistance can be divided into insulin- and non-insulin-based indices." (PMID 40416870, 2025). "In the settings of insulin resistance, this series of intracellular signaling, so-called insulin signaling, is impaired, and more insulin is needed to decrease blood glucose levels, resulting in hyperinsulinemia." (PMID 40943240, 2025). "Insulin signaling is crucial for glucose homeostasis, and its disruption can lead to insulin resistance, a key factor in the development of diabetic nephropathy (DN)." (PMID 40698245, 2025). "It notably reduced plasma glucose, insulin, hemoglobin A1c (HbA1c), and the Homeostasis Model Assessment of Insulin Resistance (HOMA-IR)." (PMID 40689212, 2025). "The data support the idea that altered Usp25m-TUG function contributes to insulin resistance, and that this occurs during fasting and independently of upstream insulin signaling." (PMID 40631311, 2025). "Adipose tissue plays a critical role in regulating energy homeostasis, insulin sensitivity, and both lipid and carbohydrate metabolism, thereby contributing to the development of insulin resistance in obesity." (PMID 40725674, 2025). "Both IL-6 and TNF-α are elevated in obesity and metabolic syndrome and can induce insulin resistance by disrupting insulin signaling pathways." (PMID 40722699, 2025). "Visceral fat promotes the release of pro-inflammatory cytokines and adipokines, which disrupt insulin signaling and contribute to systemic insulin resistance and hyperinsulinemia." (PMID 40565464, 2025). "Declining estrogen levels, particularly during menopause, can contribute to cognitive decline and insulin resistance due to the role of estrogens in insulin signaling." (PMID 41294899, 2025). "Insulin resistance in hepatocytes (p<0.01) and a compensatory insulin secretion (p<0.001) that prevented glucose intolerance were also observed in mice treated with lipotoxic Hep-sEVs." (PMID 40387904, 2025). "Traditionally, T2DM is characterized by a gradual decline in insulin secretion from the pancreas, against a background of insulin resistance." (PMID 41302503, 2025). "This is particularly relevant given that racial differences in insulin resistance, insulin sensitivity, and glycemic control have been documented." (PMID 40587474, 2025). "In contrast, in individuals with T2D, levels were disproportionately high relative to insulin due to hepatic insulin resistance." (PMID 41333061, 2025). "DM is characterised by increased blood glucose levels, often due to impaired insulin secretion from the pancreas, insulin resistance (IR) in peripheral tissues, or both." (PMID 41394217, 2025). "Conversely, decreased insulin sensitivity (insulin resistance) impairs insulin’s action on muscle and fat, potentially resulting in the loss of lean and fat mass." (PMID 40004800, 2025). "There was a significant decrease in serum concentrations of insulin and the homeostasis model assessment of insulin resistance (HOMA-IR), triglycerides, TNF-α, and TBARS with ascending quartiles of serum Se." (PMID 40564877, 2025).
Insulin resistance (continued). "Insulin resistance develops when skeletal muscle (SM), adipose tissue (AT), and the liver fail to respond adequately to insulin, a dysfunction closely intertwined with chronic low-grade inflammation." (PMID 41515940, 2025). "Tumor necrosis factor (TNF) is often secreted by macrophages and promotes insulin resistance and reduces insulin sensitivity by interfering with the insulin signaling pathway." (PMID 39950110, 2025). "Both of these factors are crucial in assessing metabolic age because increased insulin sensitivity can prevent insulin resistance, while improved circadian rhythm helps optimize overall metabolism." (PMID 40431436, 2025). "In the case of suspected insulin resistance (defined as a basal insulin level greater than 15, or an HOMA-IR greater than 2.5), patients will undergo a diagnostic OGTT to assess dynamic insulin secretion and, if necessary, initiate appropriate therapy." (PMID 40723044, 2025). "By enhancing insulin secretory capacity and reducing markers of insulin resistance, semaglutide addresses both major components of β-cell dysfunction." (PMID 41464636, 2025). "Obese rats also showed the characteristics of insulin resistance, evidenced by the significant increases in fasting plasma glucose, plasma insulin and HOMA-IR when compared with ND rats (p < 0.05)." (PMID 40076566, 2025). "Insulin resistance is characterized by either diminished pancreatic insulin secretion or impaired insulin sensitivity in target tissues, ultimately leading to elevated blood glucose levels." (PMID 40995173, 2025). "Considering that impaired glucose metabolism is closely related to decreased insulin signaling and insulin resistance, a new concept "type 3 diabetes mellitus (T3DM)" has been coined." (PMID 39966707, 2025). "One key feature of insulin resistance is the impaired ability of insulin to suppress lipolysis in adipose tissue." (PMID 39942757, 2025). "HOMA-IR, an index of insulin resistance calculated from fasting serum glucose and fasting insulin concentrations, was substantially elevated in the IS compared to EE in the OVX mice." (PMID 40173406, 2025). "In the early stages of T2DM, peripheral insulin resistance increases the demand for insulin, which in turn induces ER stress in pancreatic β-cells." (PMID 40166045, 2025). "Aging skeletal muscles exhibit mitochondrial dysfunction, intramyocellular lipid deposition, oxidative stress, and inflammatory signaling, all of which impair insulin signaling and contribute to insulin resistance." (PMID 41302993, 2025). "Insulin resistance (IR) occurs when cells inadequately respond to insulin, disrupting blood glucose homeostasis and increasing the risk of DM2." (PMID 40733199, 2025). "Alcohol consumption induces mitochondrial dysfunction, reducing ATP production, impairing insulin responsiveness, and promoting the accumulation of toxic metabolites that exacerbate insulin resistance." (PMID 40551744, 2025). "Resistin plays a role in the development of insulin resistance by interfering with the glucose-regulating activity of insulin." (PMID 41011232, 2025). "Both impaired autophagy and inhibition of ATG7 can induce disruption of the insulin pathway and insulin tolerance, meaning that decreased autophagy activity can lead to insulin resistance." (PMID 41150819, 2025). "It is characterized by hyperglycemia resulting from a combination of insulin resistance and inadequate insulin secretion by pancreatic beta cells." (PMID 41155185, 2025). "Improvements in insulin resistance were further supported by reductions in serum insulin and HOMA-IR after 6 and 12 weeks of treatment." (PMID 41465578, 2025). "TNF-α impairs insulin sensitivity by interfering with insulin signaling, and IL-6 contributes to insulin resistance by increasing hepatic glucose production." (PMID 40941639, 2025).
Insulin resistance (continued). "The Homeostatic Model Assessment of Insulin Resistance (HOMA-IR) is a validated index that is used to estimate insulin resistance based on fasting glucose and insulin levels." (PMID 40863890, 2025). "As highlighted in recent research, GDM is characterized by mitochondrial dysfunction, disruptions in insulin signaling, epigenetic alterations, and chronic inflammation, all of which contribute to insulin resistance and impaired glucose metabolism." (PMID 40361947, 2025). "This oxidative imbalance impairs β-cell function and suppresses insulin signalling pathways, driving insulin resistance." (PMID 41179869, 2025). "Homeostasis model assessment (HOMA) is a widely used method for evaluating pancreatic islet function, including the quantitative analysis of β-cell function, assessment of insulin resistance, and detection of insulin sensitivity." (PMID 39911803, 2025). "Second, SERPINA3 is strongly associated with insulin resistance and vascular disorders: SERPINA3 influences multiple cellular signalling axes, including crucial components related to insulin signalling pathways and cardiovascular remodelling." (PMID 40076571, 2025). "Type 2 diabetes mellitus (T2DM) represents the most common metabolic disorder, characterized by chronic hyperglycemia that arises from insufficient insulin secretion or insulin resistance." (PMID 41252382, 2025). "Acute reducing effects on insulin level (p = 0.013) and insulin resistance (p = 0.003) were reported after intake of Passiflora setacea pulp in overweight or slightly obese men." (PMID 41465047, 2025). "BMEE can reduce hepatic insulin resistance and the same time improve hepatic glucose uptake via the insulin and the NF‐kB signaling pathways by increasing IRS‐1 and GLUT‐2 gene expression while reducing gene expression of NFkB in the liver." (PMID 39803222, 2025). "The coexistence of insulin resistance and central obesity exacerbates this process since excess adipose tissue releases free fatty acids and inflammatory cytokines that further impair insulin signaling." (PMID 40969606, 2025). "IL‐6 triggers insulin resistance by disrupting insulin signaling and glucose transport, primarily through downregulation of IRS‐1 and GLUT‐4." (PMID 40551726, 2025). "In pediatric populations, several studies have reported an inverse relationship between serum vitamin D levels and markers of insulin resistance, such as fasting insulin and HOMA-IR." (PMID 41362334, 2025). "As expected, the DIO control mice exhibited insulin resistance, illustrated by a low iAOC for blood glucose in response to insulin, and 4h fasted blood glucose was elevated in αActRIIA/IIB-treated mice." (PMID 41022302, 2025). "UPPs also play a key role in improving insulin sensitivity, which is vital in regulating blood glucose levels, particularly in individuals with insulin resistance." (PMID 40278284, 2025). "The results demonstrate that MLD administration mitigated HFD-induced weight gain, improved insulin resistance, and enhanced glucose metabolism by reducing blood glucose and insulin levels (p < 0.05)." (PMID 40395548, 2025). "Exploratory analyses to identify subgroups revealed that individuals with mild obesity, low insulin resistance and reduced insulin secretion had a pronounced response (0.4 mmol l−1 reduction) and were consequently referred to as responders." (PMID 39929977, 2025). "The results showed a significant reduction in fasting glucose, serum insulin levels and insulin resistance levels in the study group." (PMID 39963668, 2025). "Specifically, leptin levels are negatively correlated with insulin sensitivity, with elevated leptin contributing to insulin resistance." (PMID 39942768, 2025). "Both conditions result from primary cilia dysfunction, disrupting pathways such as leptin and insulin signaling, which leads to obesity and insulin resistance." (PMID 41312179, 2025).